RNY3P5 (RNY3 pseudogene 5)
Gene: Miscellaneous RNA gene on chromosome 13 (60,789,560 to 60,789,661, forward strand). Ensembl gene ENSG00000206854.
Homologues: Orthologues: chimpanzee Y_RNA (99% identical), macaque Y_RNA (93% identical). Paralogues in human: Y_RNA (88% identical), RNY3 (87% identical), Y_RNA (87% identical), RNY3P1 (86% identical), Y_RNA (86% identical), Y_RNA (85% identical), Y_RNA (84% identical), RNY3P14 (83% identical), Y_RNA (83% identical), Y_RNA (82% identical), RNY3P10 (81% identical), RNY3P11 (81% identical), and 94 more.